CXCR4 (C-X-C motif chemokine receptor 4)
Diseases named in the same sentence as CXCR4 in open-access papers (continued):
Sharing a sentence is not in itself a finding about the gene and the disease.
infection (continued). "We compared productive infection in isolated human thymic and blood CD11c+ myeloid DC (mDC) and CD123+ plasmacytoid DC (pDC) using enhanced green fluorescent protein (EGFP) CCR5 (R5)-tropic NL(AD8) and CXCR4 (X4)-tropic NL4-3 HIV-1 reporter viruses." (PMID 21639903, 2011). "Infection studies were then performed with GHOST cells expressing CCR5 and/or CXCR4." (PMID 22141397, 2011). "The inhibitory activity of all siRNAs was previously tested in U87.CD4.CXCR4 cells with replication competent, primary isolate virus v120-A or v126-D by detecting HIV-1 reverse transcriptase activity at different time points post-infection." (PMID 21232148, 2011). "The BFLA-1 treatment of TE671 cells expressing human CD4 did not affect infection by an HIV-1 vector carrying the Env protein of the CXCR4-tropic HXB2 HIV-1 strain." (PMID 22022555, 2011). "Cystatin C did not affect the cell surface expression of CXCR4 in HeLa cells, indicating that cystatin C does not increase the CD4-independent vector infection by enhancing CXCR4 expression." (PMID 21541353, 2011). "Notably both CXCR4 and the CCR5 Env protein that mediates infection of macrophages and DCs activate Cdc42 and induce membrane extensions in iDCs." (PMID 21994805, 2011). "This confers protection in vitro and in humanized mice to infection by HIV-1 isolates that require CCR5 (but not CXCR4)." (PMID 21533216, 2011). "The second extracellular loop of this chemokine receptor is crucial for viral entry during infection with both FIV and CXCR4-specific strains of HIV, suggesting that although the primary receptor is different, the mechanism of membrane fusion is likely to be similar in both viruses." (PMID 22163340, 2011). "Treatments with these inhibitors did not reduce the cell surface expression of CXCR4, indicating that abrogation of the CD4-independent infection by the endosome acidification inhibitors is not due to the suppression of CXCR4 expression." (PMID 21541353, 2011). "The IIIBx strain retains CD4 binding activity showing enhanced fusion activity when CD4 and CXCR4 were coexpressed on target cells for fusion assays and we cannot rule out such activity contributing to infection in the assays performed in this study." (PMID 22163292, 2011). "However, it should be noted that the EC50 for gnidimacrin against NL4-3 infection is 31 pM; gnidimacrin at 50 pM only down regulated CD4 and CXCR4 by approximately 25%." (PMID 22039528, 2011). "While CXCR4 gene disruption remained stable over time at approximately 30%, CXCR4 gene disruption in HIV-infected cultures increased to 87%, 91%, and 88% in the presence of BK132, HxB2, and R3A respectively after 21 days of infection." (PMID 21533216, 2011). "For example, genes encoding several innate immune receptors and chemokines (such as TLR4, CD83, CCL2, CXCR4, CXCL5, IL1A and IL8)—several of which participate in the initiation of a T cell response during infection —showed increased relative expression in the BTB animal group." (PMID 22182502, 2011). "Little is known of the roles of phosphorylation or CXCR4 signaling on the activity of these proteins, yet HIV may modulate the activity of these proteins in a CXCR4-dependent manner to facilitate infection of the target cell." (PMID 21949786, 2011). "They enhanced or did not neutralize infection by some of the HIV-1 primary isolates using CCR5 as a coreceptor but neutralized all CXCR4 isolates tested although weakly." (PMID 21755021, 2010). "Primary infections with CXCR4-using viruses are not unusual, as thought earlier, although they are usually negatively selected during primary infection." (PMID 20646276, 2010). "Early in infection the primary coreceptor is CCR5, but during disease course CXCR4-using HIV-1 populations may emerge." (PMID 20307309, 2010).
infection (continued). "In contrast to the primate lentiviruses, all primary isolates of FIV isolated from domestic cats tested to date utilise CD134 (OX40) as a primary attachment receptor and CXCR4 as a co-receptor (CCR5 does not mediate infection with FIV)." (PMID 20420700, 2010). "However, Gfox cells are infectable with FIV field strains and infection is blocked by AMD3100, consistent with entry by CXCR4 expression." (PMID 20502526, 2010). "The 155T3 envelope, which differs from the 239 envelope by 22 amino acids in gp120, uses CXCR4 rather than CCR5 as a co-receptor for infection of both naive and memory CD4+ T lymphocytes." (PMID 19165322, 2009). "HIV's infection of a CD4+ T cell begins when HIV's outer envelope protein gp120 binds to a CD4 receptor and subsequently binds to one of two chemokine coreceptors, CCR5 or CXCR4." (PMID 19680436, 2009). "Notably, in a more recent study, in addition to CD4 and CXCR4, CCR5 was detected on the surface of megakaryocytes, and infection of these cells with both CCR5-tropic and CXCR4-tropic HIV-1 has been reported." (PMID 19112504, 2008). "The reference molecular clones Indie-C1 and NL4-3 used only CCR5 and CXCR4, respectively, for target cell infection and failed to use other coreceptors." (PMID 18328091, 2008). "The T271I mutation did not confer CD134-independent infection upon GL8 or CPG41, nor did it increase the affinity of the CXCR4 interaction, suggesting that the principal effect was targeted at reducing the complexity of the Env-CD134 interaction." (PMID 18721458, 2008). "GHOST-R3/X4/R5 cells expressing CXCR4 siRNA served as a negative control as they showed similar levels of infection seen in control non-transgenic cells with the R5-tropic virus challenge." (PMID 18667075, 2008). "Evolution of the HIV-1 phenotype during disease progression has primarily been related to coreceptor usage where early during infection viruses primarily use CCR5 (the R5 phenotype), and later during disease progression, viruses with the ability to use CXCR4 emerge (the X4 phenotype)." (PMID 18371209, 2008). "We also observed a partial down-regulation of CXCR4 in primary human peripheral blood mononuclear cells after infection of HIV-1 (not shown)." (PMID 18190699, 2008). "When challenged with X4-tropic HIV-1 NL4.3, GHOST-R3/X4/R5 cells expressing CXCR4 siRNA showed a 10 fold decrease in virus production as compared to control non-transgenic cells on day 10 post-infection." (PMID 18667075, 2008). "While primary monocyte derived macrophages (MDM) express CD4 and CCR5 and a low level of CXCR4, they support productive infection of R5 but not X4 viruses." (PMID 18036244, 2007). "Infection of U373-Magi-X4 and U373-Magi-R5 cell lines indicate that all our chimeric viruses and the control R5-tropic isolate HIV-1BaL, utilized the CCR5 coreceptor, whereas the parental HIV-1NL4-3 utilized the CXCR4 coreceptor." (PMID 18036244, 2007). "Finally, an in vivo mouse model of E. coli pneumonia demonstrated that CXCR4+ and CD69+ T cells are rapidly recruited from the blood to the lung during the peak of infection further supporting the role of the ALARM module in mediating immune cell recruitment to sites of inflammation." (PMID 41531734, 2026). "VitD’s potential upregulation of CXCR4 could result from increased expression of its ligand, stromal cell-derived factor 1 (SDF1 or CXCL12), also predicted by the model, which has been observed to impede HIV entry, protecting against infection." (PMID 40149968, 2025). "HIV-2 strains are generally more promiscuous than HIV-1 strains in their use of co-receptors, but CCR5 and CXCR4 appear to still be the major co-receptors for infection, and it is not clear whether use of the other co-receptors is relevant in vivo." (PMID 40507836, 2025).
infection (continued). "In the blood, CXCR4+ neutrophils show no significant changes in either Delta- or Omicron-infected cats compared to controls, suggesting that this subset was not actively involved in systemic circulation during the infection." (PMID 40475786, 2025). "To test this hypothesis, we knocked out CPSF5 in primary CD4+ T cells using two independent guide RNA in three independent donors and conducted HIV-1 spreading infection assays as before alongside non-targeting, CXCR4 knock-out, and CYPA knock-out controls." (PMID 39678349, 2024). "Genome editing of CCR5 during the first months of infection may prevent or delay infection of new cells and achieve treatment-free control of infection without the need for targeting CXCR4 or other host factors with genome editing." (PMID 39459922, 2024). "Despite the sparsity of the observed substantial differences in signatures of CXCR4- and CCR5-tropic latency, we have noticed that among genes identified in our dataset, the interleukin 7 receptor (IL7R) was upregulated in latently infected cells for CCR5-tropic infection only." (PMID 38156317, 2023). "Furthermore, a recent study on patients infected with the mumps virus (MuV) reported significantly increased expression of CXCR4 (derived as a bone marrow–homing marker) in MuV-specific CD8+ T cells of the peripheral blood between 1.5 and 9 months after infection." (PMID 37824612, 2023). "Interestingly, transdifferentiated BLaER1 cells displayed HIV-1 entry receptor CD4 expression and high surface level expression of both co-receptors CXCR4 and CCR5 indicating that they may be amenable to infection with CCR5- and CXCR4-tropic HIV-1." (PMID 37800914, 2023). "The percentages of the CXCR4-tropic virus in B (3.7%) and CRF01_AE (10.4%) infection are much higher than that of CRF07_BC (0.1%), which is supported by median false-positive rates (FPRs) of 69.8%, 25.5%, and 13.4% for CRF07_BC, B, and CRF01_AE respectively, with a cutoff FPR for CXCR4-tropic at 2%." (PMID 36211390, 2022). "Similarly, the transduced cells were inoculated with three CXCR4-tropic (NL4-3, SG3.1, and LAI.2) and three CCR5-tropic (RHPA.c/2635, TRJO.c/2851, and MJ4) viruses, and infections were monitored over time by detecting intracellular HIV-1 p24 antigen and GFP expression." (PMID 34821542, 2022). "The TZM-bl cell line is a derivative of HeLa cells that express CD4, CCR5, and CXCR4 and contains an integrated reporter gene for firefly luciferase and E. coli β-galactosidase under the control of an HIV-1 long terminal repeat (LTR), permitting sensitive and accurate measurements of infection." (PMID 34578431, 2021). "Similarly, the presence of CXCR4-using viruses in the very early stages of infection does not necessarily translate into accelerated progression of the disease." (PMID 33872329, 2021). "Although we observed changes in both PD-1 and CXCR4 expression between 1.5 and 9 months post-infection, the expression of these T-cell inhibitory and homing markers 1.5 months post-infection did not explain the decline in MuV-specific T-cell frequencies in the convalescence phase." (PMID 34960178, 2021). "Prior studies have shown that TN can be infected in vitro with CXCR4-tropic HIV-1 when pretreated with the chemokine CCL-19, the ligand for the CCR7 receptor, expression of which significantly increases during the acute phase of infection when the latent reservoir is established." (PMID 33688006, 2021). "Phenotypic tropism assays revealed that lentivirus reporters pseudotyped with 75 (80.6%) and 5 (5.4%) envelope clones could establish infection toward U87.CD4 cells expressing CCR5 (R5) and CXCR4 (X4), respectively; whereas the remaining 13 (14%) clones could infect both cells." (PMID 34305873, 2021).
infection (continued). "Consistent with the data showing a lack of an effect on peroxisome biogenesis factor levels, infection with HIV-1 harboring mutated Vpu did not significantly increase the expression of miR-500a-5p, miR-34c-3p, miR-93-3p, or miR-381-3p in HeLa-CD4/CXCR4/CCR5 cells, macrophages, or T cells." (PMID 32127461, 2020). "Inhibition of CXCR4 activity by a single s.c. injection of AMD3100 (100 μg/foot skin), a selective CXCR4 antagonist, administered 2 h prior to infection failed to alter viral loads in the pLN of Wt and TLR7−/− mice as compared to vehicle treated littermate controls." (PMID 30930901, 2019). "However, inactivation of the CCR5 does not prevent infection with CXCR4-tropic and dual-tropic viruses and is likely to select for variants that can utilize the CXCR4 coreceptor, suggesting a need for strategies to suppress infection with CCR5-, CXCR4-, and dual-tropic viruses." (PMID 31778955, 2019). "In addition, the HIV env gp120 was demonstrated to induce hepatocyte apoptosis in vitro through CXCR4 in the absence of infection, thus triggering the pro-fibrotic activity of HSC." (PMID 29324755, 2018). "With regards to the liver, hepatic macrophages do not support viral replication in vivo and also express low levels of CD4 and co-receptors, CCR5/CXCR4, suggesting they may not be permissive to infection." (PMID 29466439, 2018). "CXCR4 is expressed on the majority of CD4+ T cells; however, CXCR4-tropic HIV-1 variants account for only a fraction of viruses worldwide and almost none that are involved in transmission and early infection." (PMID 29970186, 2018). "Furthermore, mice that were administered a ZFN-modified transplant but were infected with a CXCR4-utilizing HIV-1 strain did not demonstrate an elevated resistance to infection." (PMID 30619107, 2018). "This infection could be blocked by respective CCR5 and CXCR4 inhibitors." (PMID 28060951, 2017). "Previously, we demonstrated that BBB pericytes express the chemokine receptors CXCR4 and CCR5, two major co-receptors for HIV-1 entry, and that their infection may contribute to the progression of HIV-induced CNS damage by causing BBB disruption and increasing endothelial permeability." (PMID 29311803, 2017). "Anti-C17 could dose dependently inhibit the infection of CCR5-tropic JRFL virus at an IC50 of 0.40 μM without any inhibition on CXCR4-tropic HXB2 virus." (PMID 28484468, 2017). "To test whether alteration of CXCR4 can confer protection to HIV-1NL4-3 virus, we infected modified Jurkat T cells with HIV-1NL4-3 virus and performed p24 antigen ELISA assays at 1, 3, 5 and 7 days post infection." (PMID 26481100, 2015). "Nef effect on CXCR4 was recapitulated in T cell lines and monocytes transduced with bacterially expressed hexa-His-tagged myristoylated Nef containing TAT-Arginine-rich motifs (RRMs) and in single cycle infection of CEM cells with VSV-G pseudotyped Nef (+) and Nef (−) HIV." (PMID 24489825, 2014). "The results reveal that viral progeny was detected in all culture supernatants; however, we could not detect in any occasion the productive infection of pure GHOST-CD4/CCR5 or GHOST-CD4/CXCR4 cells (data not shown)." (PMID 25421818, 2014). "Surprisingly, high frequency of the predicted CXCR4-tropic viruses also existed in other CD4+T cell stratified groups, especially in CD4+T cell count≥500 (40.7% in algorithm I and 37% in algorithm II), similar to the observation among subtype D infection in Kenya’s study." (PMID 24586795, 2014). "Although numerous studies have attempted to correlate the predominance of CCR5-tropic strains during the early stage of infection with a biological bottleneck inherent to the genital mucosa, no conclusive evidence has been provided to indicate that CXCR4-tropic viruses were less transmissible." (PMID 24586795, 2014).
infection (continued). "Cells expressing EGS C1 appeared to be resistant to infection by M-tropic HIVBa-L strain but remain very susceptible to infection by T tropic HIVIIIB strain, suggesting that C1 specifically targeted CCR5 but not CXCR4." (PMID 23509733, 2013). "In addition, the ligation of OX40 has also been shown to inhibit infection by CCR5-utilizing (R5) but not CXCR4-utilizing (X4) human immunodeficiency virus type-1 (HIV-1) via enhancement of production of CCR5-binding β-chemokines." (PMID 24238037, 2013). "Infection with both low and high virulence isolates resulted in down-regulation of mRNA levels for chemokines CCL2, CCL3L, CXCL2 and chemokine receptors CCR1, CCR5, CXCR3, CXCR4 and up-regulation in expression of mRNAs for CCL4, CXCL10 and chemokine receptor CCR7." (PMID 23265239, 2013). "We then analyzed whether lung DCs from the infection models differ in their potential capabilities to enter the lung draining lymph nodes, as analyzed by the frequency of CD11c+ cells that express CCR7 and CXCR4." (PMID 23300813, 2012). "It is not clear whether these effects require infection or result from extracellular gp120 interactions with CXCR4 and CCR5." (PMID 22479424, 2012). "We have previously shown successful mucosal transmission in RAG-hu mice for both CCR5 tropic and CXCR4 tropic strains introduced both vaginally and rectally, although a lower rate of infection was observed with CXCR4 strains which are not effectively transmitted sexually in humans." (PMID 21835012, 2011). "Thus, the PBMCs infected with low levels of HIV-1 (at a multiplicity of infection of lower than 0.01) were cultured for 5 days in the presence or absence of 10 μg/ml of either anti-CXCR4 mAb or isotype control." (PMID 22018245, 2011). "In order to determine if spinoculation was masking subtle differences in the susceptibility to infection, we infected CD4+ T cells with CXCR4-tropic virus without spinoculation and again found that CD4+ T cells from patient 169 were fully susceptible to infection." (PMID 22141397, 2011). "In contrast, CXCR4 was expressed only on the DCs and not on microglia during infection." (PMID 21949652, 2011). "Future studies can also address potential differences between signaling of CXCR4 and CCR5, another HIV-1 coreceptor, since differential engagement of these chemokine receptors can have unique effects on target gene expression and host factor requirements for infection of primary cells." (PMID 21949786, 2011). "However, some mutants have an advantage as they may allow escape from immune surveillance or more effective infection of certain tissue compartments or cell types, such as cells in the brain or the genital tract or naïve CD4+ T-cells, which express CXCR4." (PMID 21829600, 2011). "It has been repeatedly shown that various SIV isolates can infect primary human Δ32 homozygous PBMC independent of both CCR5 and CXCR4, indicating that alternative coreceptors are expressed in a manner that supports infection in primary lymphocytes ex vivo, at least in cells of human origin." (PMID 20865163, 2010). "HBD2 is reported to inhibit infection through direct interaction with the virus, as well as decreasing expression of CXCR4, the co-receptor for X4 HIV-1 viruses (but not CCR5) in peripheral blood mononuclear cells and T lymphocytic cells as shown by confocal microscopy and flow cytometry." (PMID 20614007, 2010). "However, PSSM score was significantly increased (indicating greater CXCR4 usage) in those with stage 4 (β = 6.34, p = 0.0002) but not stage 2 or stage 3 infection (p = 0.8 each)." (PMID 21187897, 2010). "Taken these thoughts further, different subtypes and CRFs may be more or less predisposed for the emergence of R5X4 or X4 populations, although it seems that CXCR4-using HIV-1 populations likely will arise in most HIV-1 non-subtype C infections." (PMID 20307309, 2010). "None of the viruses exclusively used the CXCR4 co-receptor for infection." (PMID 19442296, 2009).